CRYBG2 (crystallin beta-gamma domain containing 2)
Synonyms: AIM1L; FLJ38020
Tractability: PROTAC: ubiquitination databases record sites on it.
Safety:
Unwanted effects reported when the protein is acted on. In parentheses: how it was acted on, where the effect was seen, and who reports it.
nausea and vomiting (source: ClinPGx)
Gene: Protein-coding gene on chromosome 1 (26,321,698 to 26,360,080, reverse strand). Ensembl gene ENSG00000176092.
Subcellular location (Human Protein Atlas): Nucleoplasm
Genetic constraint (gnomAD): Loss-of-function variants: 103 observed, 138.74 expected, observed/expected ratio (o/e) 0.74, 90% interval 0.63 to 0.87. The upper end of that interval is the gene's LOEUF score, 0.87, which puts it in group 3 of 6, group 1 being the genes least tolerant of losing a copy. Missense variants: 1,956 observed, 1,990.7 expected, observed/expected ratio (o/e) 0.98, 90% interval 0.95 to 1.02. Synonymous variants: 835 observed, 813.43 expected, observed/expected ratio (o/e) 1.03, 90% interval 0.97 to 1.09.
Homologues: Orthologues: chimpanzee CRYBG2 (98% identical), macaque CRYBG2 (92% identical), pig CRYBG2 (69% identical), rabbit CRYBG2 (69% identical), guinea pig CRYBG2 (69% identical), dog CRYBG2 (68% identical), mouse Crybg2 (67% identical), rat Crybg2 (66% identical), tropical clawed frog crybg2 (32% identical), zebrafish prdm1b (23% identical). Paralogues in human: CRYBG1 (23% identical), CRYBG3 (19% identical), CRYBB1 (5% identical), CRYBB3 (4% identical), CRYBA4 (4% identical), CRYBA1 (4% identical), CRYBB2 (4% identical), CRYGC (3% identical), CRYGA (3% identical), CRYBA2 (3% identical), CRYGD (3% identical), CRYGB (3% identical), and 2 more.
Diseases named in the same sentence as CRYBG2 in open-access papers:
CRYBG2 is named in the same sentence as 22 diseases in open-access papers, as found by Europe PMC text mining. Sharing a sentence is not in itself a finding about the gene and the disease. The quoted sentences say what the papers report.
esophageal cancer (1 paper, 2024). A primary or metastatic malignant neoplasm involving the esophagus. "The positively correlated genes (SLUT2B1, PPL, KLK6, CRYBG2, SCEL, ADGRF4 and KLK8) were more frequently expressed in esophageal cancer than normal tissue (p < .05)." (PMID 38241178, 2024).
CRYBG2 also shares sentences with these, for which no sentence is quoted: tumor (3 papers); breast carcinoma (2); cancer (2); colon cancer (2); esophageal squamous cell carcinoma (2); hepatocellular carcinoma (2); malignant melanoma (2); ovarian carcinoma (2); asthma (1); bladder cancer (1); bladder inverted papilloma (1); cataract (1); endometrial cancer (1); lens diseases (1); liver cancer (1); liver fibrosis (1); Obesity (1); pancreas cancer (1); prostate carcinoma (1); prostatic (1); viral myocarditis (1).